PRDX6 (peroxiredoxin 6)
Diseases named in the same sentence as PRDX6 in open-access papers (continued):
Sharing a sentence is not in itself a finding about the gene and the disease.
metabolic disease (7 papers, 2018 to 2025). A congenital disorder (due to inherited enzyme abnormality) or acquired (due to failure of a metabolically important organ) disorder resulting from an abnormal metabolic process. "According to research, Prdx6 might be suggested as a novel therapeutic target for the treatment and prevention of metabolic disorders linked to accelerated aging." (PMID 40313876, 2025). "Although we did not study aged Prdx6 KO or mutant mice, previous results suggest that Prdx6-deficient animals exhibit increased susceptibility to oxidant stress in aging, a sarcopenic-like phenotype, and potentially other aging-related metabolic diseases [39,]." (PMID 40774144, 2025). "The specific role of Prdx6 peroxidase and aiPLA2 activities in the development and progression of metabolic disease remains unexplored." (PMID 30477202, 2018). "Similarly to Prdx6, SIRT1 has shown to modulate insulin release and to be implicated in metabolic disorders." (PMID 32316601, 2020). "Consequently, the lack of a protective effect of PRDX6 overexpression may lead to the development of metabolic disorders." (PMID 34063343, 2021).
neurological disorders (7 papers, 2010 to 2025). "Nevertheless, the underlying mechanisms of action for Prdx6 in neurological disorders have largely remained elusive." (PMID 38671897, 2024). "Along with others, we have shown that PRDX6 blocks ROS-mediated pathophysiology that occurs during cataractogenesis, neurological disorders, and diabetic-associated disorders, and plays a pivotal role in maintaining lung cell homeostasis." (PMID 20923568, 2010). "This review discusses the distinctive structure, enzyme activity, and function of Prdx6 in different CNS disorders, as well as emphasizing the significance of Prdx6 in neurological disorders." (PMID 38671897, 2024). "Therefore, this review seeks to unveil the significance of Prdx6 in CNS disorders, which will contribute to a greater understanding about the potential value of Prdx6 as a new therapeutic target for neurological diseases." (PMID 38671897, 2024). "Thirteen OB proteins were differentially regulated in at least three neurological disorders, of which four of them (NCAM2, LY6H, COL6A3 and PRDX6) presented a homogeneous OB profile across diseases." (PMID 34768771, 2021). "Peroxiredoxin 6 is the only 1-Cys member and exhibits bifunctional activities as a glutathione (GSH) peroxidase and calcium-independent phospholipase A2 (PLA2), which might contribute to neurological disorders." (PMID 23210548, 2012).
neurodegenerative disease (5 papers, 2013 to 2024). A disorder of the central nervous system characterized by gradual and progressive loss of neural tissue and neurologic function. "Even though it is possible that inducible phospholipase A2 (iPLA2) activity of PRDX6 could be associated with cell death and blocking of neurogenesis because iPLA2 is critical in the development of neurodegenerative diseases." (PMID 30097850, 2019). "The role of peroxiredoxin 6 (PRDX6) in neurodegenerative diseases is very controversial." (PMID 30097850, 2019). "Taken together, these studies indicated that PRDX6 inhibits neurogenesis of neural stem cells through downregulation of WDFY1-mediated TLR4 signaling pathway and suggest that the inhibitory effect of PRDX6 on neurogenesis plays a role in the development of neurodegenerative disease." (PMID 30097850, 2019).
psychiatric disorder (2 papers, 2012 to 2016). A disorder characterized by behavioral and/or psychological abnormalities, often accompanied by physical symptoms. "It is noted that 7 genes, DAO, PRDX6, KCNN3, TCF7L2, RFX4, FYN, and B3GAT2 (yellow-colored nodes), relevant to psychiatric disorders are involved and interestingly these genes except B3GAT2 constitute a connected subgraph." (PMID 27510319, 2016).
adenocarcinoma (1 paper, 2020). A common cancer characterized by the presence of malignant glandular cells. "However, only PRDX2, PRDX3, and PRDX6 expression was associated with worse OS in adenocarcinoma patients." (PMID 32908916, 2020). "Moreover, PRDX2 and PRDX6 exhibited stronger connections than PRDX3 in adenocarcinoma patients." (PMID 32908916, 2020).
brain diseases (1 paper, 2024). "Although previous studies about the roles of Prdx6 in brain diseases are somewhat controversial, Prdx6 appears to work primarily via Gpx and aiPLA2 activities to reduce oxidative stress." (PMID 38671897, 2024). "Therefore, Prdx6 might represent a potential and alternative target for therapeutic intervention in brain diseases." (PMID 38671897, 2024).
CNS disorders (1 paper, 2024). "Therefore, it may play contradictory roles in different models of the same disease, which makes it more difficult and complex to study the function of Prdx6 in CNS disorders." (PMID 38671897, 2024).
inflammation (1 paper, 2022). Aberrant reaction of the microcirculation characterized by movement of fluid and leukocytes from the blood into extravascular tissues. "In the lipopolysaccharide (LPS)-induced lung injury mouse model, inactivation of the aiPLA2 activity of Prdx6 was associated with reduced mortality and prevention of lung inflammation and oxidative stress." (PMID 35549905, 2022).
musculoskeletal diseases (1 paper, 2025). "Here, we hope that this review will provide new ideas and references for relevant researchers, and also hope that more researchers will study the specific mechanism of Prdx6 in musculoskeletal diseases, find its ideal target drugs, and write a new chapter for the treatment of MSDs." (PMID 40313876, 2025).
respiratory diseases (1 paper, 2023). "In this paper, the role of PRDX6 in oxidative stress in respiratory diseases and the research progress in targeting PRDX6 are reviewed." (PMID 36611974, 2023). "The peroxidase and phospholipase A2 activity of PRDX6 is closely related to its anti-oxidant and pro-oxidant effects, which leads to the conflicting regulatory effects of PRDX6 on oxidative stress in respiratory diseases." (PMID 36611974, 2023). "PRDX6 has become a new target in respiratory disease research due to its important regulatory role in oxidative stress." (PMID 36611974, 2023).
PRDX6 also shares sentences with these, for which no sentence is quoted: bacterial infection (5 papers); diabetic retinopathy (3); oligodendroglioma (3); brain injury (2); depression (2); esophagogastric junction adenocarcinoma (2); multiple sclerosis (2); non-alcoholic fatty liver disease (2); Pick disease (2); thyroid cancer (2); type 2 diabetes (2); abdominal aortic aneurysm (1); Alexander disease (1); anaplastic oligodendroglioma (1); brain tumors (1); cardiovascular diseases (1); cervical (1); Chagas disease (1); chronic hepatitis (1); chronic obstructive pulmonary disease (1); colon (1); dementia with Lewy bodies (1); dysplasia (1); endometrioid ovarian cancer (1); endometriosis (1); fungal infection (1); gastric cancer (1); glioblastoma (1); Graves’ orbitopathy (1); head and neck carcinoma (1).
A further 25 diseases each share a sentence with PRDX6 in 1 paper.